ICA1 (islet cell autoantigen 1)
Description:
May play a role in neurotransmitter secretion.
Synonyms: ICA69; ICAp69
Tractability: Antibody: UniProt places it where antibodies can reach, with high confidence. PROTAC: its protein half-life has been measured.
Gene: Protein-coding gene on chromosome 7 (8,113,181 to 8,262,687, reverse strand). Ensembl gene ENSG00000003147.
Subcellular location: Cytoplasm, cytosol; Golgi apparatus membrane; Cytoplasmic vesicle, secretory vesicle membrane; Cytoplasmic vesicle, secretory vesicle, synaptic vesicle membrane
Subcellular location (Human Protein Atlas): Cytosol; Vesicles
Gene Ontology:
Molecular function: membrane curvature sensor activity; protein binding; protein domain specific binding
Biological process: membrane bending; regulation of secretion
Cellular component: cytosol; Golgi membrane; secretory granule membrane; cytoplasm; synaptic vesicle membrane; endomembrane system; transport vesicle membrane
Genetic constraint (gnomAD): Loss-of-function variants: 29 observed, 52.74 expected, observed/expected ratio (o/e) 0.55, 90% interval 0.41 to 0.75. The upper end of that interval is the gene's LOEUF score, 0.75, which puts it in group 3 of 6, group 1 being the genes least tolerant of losing a copy. Missense variants: 459 observed, 492.57 expected, observed/expected ratio (o/e) 0.93, 90% interval 0.86 to 1.01. Synonymous variants: 179 observed, 184.99 expected, observed/expected ratio (o/e) 0.97, 90% interval 0.86 to 1.1.
Homologues: Orthologues: chimpanzee ICA1 (99% identical), macaque ICA1 (98% identical), dog ICA1 (94% identical), pig ICA1 (93% identical), guinea pig ICA1 (93% identical), mouse Ica1 (89% identical), rabbit ICA1 (89% identical), rat Ica1 (89% identical), tropical clawed frog ica1 (67% identical), zebrafish ica1 (53% identical), Drosophila melanogaster ICA69 (31% identical), Caenorhabditis elegans ric-19 (30% identical). Paralogues in human: ICA1L (50% identical).
Diseases named in the same sentence as ICA1 in open-access papers:
ICA1 is named in the same sentence as 44 diseases in open-access papers, as found by Europe PMC text mining. Sharing a sentence is not in itself a finding about the gene and the disease. The quoted sentences say what the papers report.
prostate carcinoma (13 papers, 2007 to 2025). A carcinoma that arises from epithelial cells of the prostate gland. "Two genes, Usb1 and Lrig3, have recently been studied as therapeutic targets in poikiloderma with neutropenia and prostate cancer, respectively, while Ica1 encodes an autoantigen involved in autoimmune insulin-dependent diabetes mellitus and primary Sjogren’s syndrome." (PMID 36818345, 2023).
diabetes (11 papers, 2012 to 2025). "ICA1 encodes a protein involved in the regulation of secretory vesicle trafficking and has been implicated as an auto-antigen in insulin-dependent diabetes mellitus and primary Sjögren's syndrome." (PMID 23836780, 2013). "It must also be noted that ICA1, coding for ICA69 autoantigen, has been previously associated with Diabetes mellitus type 1 (T1DM), based on cDNA expression analysis in islet cells, as well as being implicated in SS." (PMID 26031516, 2015). "Islet cell autoantigen 1 (ICA1) is believed to be an autoantigen in insulin-dependent diabetes mellitus." (PMID 23029078, 2012). "Importantly, sQTLs also affected genes that harbor variants that cause monogenic diabetes (KCNK16, ABCC8, PDX1) or influence T2D risk (THADA, PAM) as well as genes that play a role in T1D pathogenesis (ICA1, PTPRN2, HLA-B)." (PMID 36109769, 2022). "ICA1 codes for islet cell autoantigen 69 (ICA69), an autoantigen of diabetes mellitus and Sjögren’s syndrome." (PMID 40725187, 2025). "The top diabetes-related antigens were GAD, insulin, IA-2/PTPRN, IGRP, ZnT8, HSP, and ICA-1, representing nearly 90% of the captured data." (PMID 25140192, 2013).
type 1 diabetes (8 papers, 2012 to 2023). "Islet cell autoantigens, including ICA1, have been associated with the development of type I diabetes mellitus, and there is defined structural and pathway evidence linking the gene product to disease." (PMID 30941163, 2019). "Islet cell autoantigen 1 (ICA1) which is associated with SLE was previously known to function as an autoantigen in type I diabetes mellitus." (PMID 27933432, 2017). "The most important beta cell autoantigens in type 1 diabetes (Ins1/2, Slc30a8, Ica1, Gad1, Ptprn2) were expressed at higher levels in Zbed6-KO islets." (PMID 34296320, 2021). "However, ICA69 alone is not obligatory for type 1 diabetes because Ica1-knockout (KO) mice showed no obvious phenotype and aged normally unless they were crossed with non-obese diabetic mice, a well-established animal model for type 1 diabetes." (PMID 37251649, 2023).
Alzheimer disease (3 papers, 2023 to 2024). A progressive, neurodegenerative disease characterized by loss of function and death of nerve cells in several areas of the brain leading to loss of cognitive function such as memory and language. "Databases related to Alzheimer's disease (AD) have shown decreased ICA1 expression in patients with AD." (PMID 38884369, 2024).
autoimmune disease (2 papers, 2015 to 2024). A disorder resulting from loss of function or tissue destruction of an organ or multiple organs, arising from humoral or cellular immune responses of the individual to their own tissue constituents. "Islet cell autoantigen 1 (ICA1) is involved in autoimmune diseases and may affect synaptic plasticity as a neurotransmitter." (PMID 38884369, 2024).
Autoimmunity (2 papers, 2015 to 2017). The occurrence of an immune reaction against the organism's own cells or tissues. "In addition to the genes above, it is also clear that this approach identified well known genes associated with autoimmunity within the exome variant data of these patients, which in this case are ICA1 and STAT6 (encoded by the same variant as LRP1)." (PMID 26031516, 2015). "Recently, it was shown that polymorphisms in ICA1 promoter may alter binding of the transcription factor AIRE, resulting in downregulation of ICA1 expression in medullary thymic epithelial cells leading to loss of immunologic tolerance to this self-antigen and triggering autoimmunity." (PMID 27933432, 2017). "Further, ICA1 and STAT6 were also closely related to AIRE and IRF5, two very well known autoimmunity genes." (PMID 26031516, 2015).
cardiomyopathy (2 papers, 2022 to 2023). A disease of the heart muscle or myocardium proper. "We discovered that those data presented certain resemblance relative to the mouse experiments, highlighting that targeting ICA1 could serve as a cardioprotective strategy for cardiomyopathy prevention." (PMID 35397620, 2022).
glaucoma (2 papers, 2013 to 2014). Increased pressure in the eyeball due to obstruction of the outflow of aqueous humor. "ICA1 was also identified in a GWAS looking at genetic modifiers of glaucoma." (PMID 25418976, 2014).
autism spectrum disorder (1 paper, 2023). A spectrum of developmental disorders that includes autism, and Asperger syndrome. "Recently, several human genetics studies have discovered that a de novo Ica1 mutation and copy number variations are associated with autism spectrum disorder and intellectual disability." (PMID 37251649, 2023).
insulinoma (1 paper, 2015). "It has been found that overexpression of ICA1 in insulinoma INS-1 cells impairs secretory granule protein transport." (PMID 26578562, 2015).
RASopathy (1 paper, 2017). Developmental syndromes caused by germline mutations (or in rare cases by somatic mosaicism) in genes that alter the Ras subfamily and mitogen-activated protein kinases that control signal transduction. "Additional genes listed in SFARIgene adjacent to our top RASopathy social responsiveness QTL results include CNTN5, ESRRB, GABRB1, GNB1L, and ICA1." (PMID 28076348, 2017).
systemic sclerosis (1 paper, 2015). A chronic disorder, possibly autoimmune, marked by excessive production of collagen which results in hardening and thickening of body tissues. "Collectively, our data suggest that rs6948664 is a likely causal variant for SLE or systemic sclerosis by significantly affecting ICA1's expression level and/or protein output." (PMID 26578562, 2015).
infection (10 papers, 2009 to 2025). The state of being infected such as from the introduction of a foreign agent such as serum, vaccine, antigenic substance or organism. "Differences in Ica1 protein structure or expression can affect the sympathetic nervous system activity and neuropeptide secretion altering the host response to infection." (PMID 25418976, 2014). "The most common infection regions were the abdomen and lung, and the region distribution resembled each other in survival and mortality group, the latter of which registered a notably higher ICA1 level." (PMID 35397620, 2022).
cancer (5 papers, 2017 to 2025). A tumor composed of atypical neoplastic, often pleomorphic cells that invade other tissues. "The other two genes, ICA1 and PSMB1, were observed displaying very strong intensity in cancer tissues." (PMID 35909904, 2022). "Based on the expression profiles of 5 genes, PCA showed that normal and cancer samples were clearly separated, with COMP, ICA1, and PSMB1 contributing to PC1 and ACAA1 and with SCGB2A1 contributing to PC2." (PMID 35909904, 2022). "Although ICA-1-mediated reduction in cell proliferation in several cancer cells or in cancer animal models has been reported, there are no studies on its application in the clinical trials." (PMID 34834162, 2021).
ICA1 also shares sentences with these, for which no sentence is quoted: tumor (7 papers); Sjögren’s syndrome (5); breast carcinoma (3); benign prostatic hyperplasia (2); Sepsis (2); viral infection (2); adenoma (1); Anxiety (1); bladder cancer (1); cardiovascular disease (1); colorectal cancer (1); dementia (1); developmental delay (1); glioma (1); Glucose intolerance (1); immune disorders (1); Impaired glucose tolerance (1); Intellectual disability (1); kidney cancer (1); lacrimal gland disease (1); lung carcinoma (1); metabolic syndrome (1); microcephaly (1); neurological disorders (1); neutropenia (1); prostate (1); rheumatoid arthritis (1); schizophrenia (1); Stroke (1); type 2 diabetes (1).